CCND1 (cyclin D1)
Diseases named in the same sentence as CCND1 in open-access papers (continued):
Sharing a sentence is not in itself a finding about the gene and the disease.
tumor (continued). "Furthermore, p-AKT, p-mTOR, p-4E-BP1, and cyclin D1 expression levels in epithelial ovarian and peritoneal tumors were shown not to be associated with partial/complete tumor responses to Temsirolimus, however cyclin D1 expression seemed to correlate with PFS ≥6 months." (PMID 22970424, 2012). "Cyclin D1, a member of G1 cyclins, and PCNA (proliferating cell nuclear antigen) are commonly used to assess tumor cell proliferation." (PMID 22879971, 2012). "STAT3 activation can upregulate the expression of anti-apoptotic proteins (Bcl-2, Mcl-1 and Bcl-x), proliferation related proteins (cyclin D1 and c-Myc) and angiogenesis promoting factors (VEGF) to prevent tumor cells from apoptosis." (PMID 23554768, 2012). "The transcription of genes required for the G1/S transition such as Cyclin E and Cyclin D1 is initiated by E2F1, which is under the control of the Rb tumor suppressor." (PMID 23028659, 2012). "We also stained tumor sections with antibodies specific to phosphorylated 4E-BP1 and oncogenic and growth promoting proteins such as cyclin D1, cyclin E, c-Myc, Bcl-2, and VEGF." (PMID 22935625, 2012). "These tumor suppressive effects of miR-34a are mediated by changes in a number of target mRNAs including MYCN, CDK4, cyclin D1, SIRT1 and Bcl-2." (PMID 22629428, 2012). "In conclusion, a putative tumor suppressor, BLU, plays a vital role in growth inhibition in NPC malignancies via JNK and cyclin D1 promoter inhibition." (PMID 22727408, 2012). "PDTC treatment inhibited the expression of the key cell cycle regulators cyclin D1, cyclin E1, and PCNA in both tumors and in non-tumor bearing epidermis." (PMID 22761871, 2012). "Benign tumour cells showed a higher expression of p16INK4a pathway members (p16INK4a, E2F1 and cyclin D1) compared with normal salivary gland." (PMID 21917131, 2011). "One of the important points of the present study is that cyclin D1 expression in tobacco-related OSCC showed a significant correlation with clinicopathological features of patients and tumours as well." (PMID 21537090, 2011). "The present study identified that the expression ratio of CCND1/CDKN2A predicts the status of RB1 in both cultured cancer cell lines and clinical tumor samples." (PMID 21447152, 2011). "The results showed the protein levels of EGFR and AKT were decreased in the tumor homogenates in both curcumin alone and curcumin combined with gefitinib groups, whereas, the c-MET, cyclin D1, and PCNA were also down-regulated simultaneously." (PMID 21858220, 2011). "To further corroborate these findings, we investigated the ability of 25HC to modulate the expression of ERα and Cyclin D1 protein levels in MCF7 and BG-1 tumor cells." (PMID 21304949, 2011). "We report here that the CCND1/CDKN2A mRNA expression ratio predicts the RB1 status of cell lines in vitro and xenograft tumors and clinical tumor samples in vivo." (PMID 21447152, 2011). "Altogether, these data suggest that the increased proliferation and tumor growth are LPP3-specific and mediated by increased β-catenin and CYCLIN-D1 functional activity." (PMID 21569306, 2011). "Cyclin D1 regulates vascular endothelial growth factor (VEGF) production and thereby, growth of vascular endothelial cells and tumor." (PMID 20459741, 2010). "The tumor lysates were analyzed for the expressions of OPN, c-Jun, cyclin D1 and uPA by western blot and RT-PCR." (PMID 20609221, 2010).
tumor (continued). "Many proteins that are crucial for tumor cell proliferation and survival have been found to be regulated by STAT3; these include Bcl-2, Bcl-XL, cyclin D1/D2 and IL-6, which are considered to contribute to the anoikis resistance-inducing property of STAT3." (PMID 20507639, 2010). "Cyclin D1 and PCNA were expressed by terminal duct epithelial cells, gland alveolus cells and tumor cells." (PMID 20092659, 2010). "Expression of cyclin D1 and Ki67 (all proteins located downstream of the BRAF kinase) were analyzed by immunohistochemistry in paired tumor biopsies (pre- and post treatment) from 15 of 36 patients." (PMID 21206909, 2010). "The tumor samples were analyzed by immunofluorescence using anti-OPN, anti-c-Jun, anti-cyclin D1 and anti-uPA antibodies." (PMID 20609221, 2010). "More interestingly, the CD4 T cells from the HLA-DR.B1-matched donors are also able to kill the peptide-pulsed autologous DCs and more importantly, a tumor cell line, MDA-MB-231, expressing a high level of cyclin D1." (PMID 19707583, 2009). "The CCND1 and HER-2/Neu genes were more often positioned at the periphery (mean frequency of 60%-83%) of the CTs in tumor tissues of the esophagus and stomach." (PMID 21637674, 2009). "A common phenomenon of tumour formation is the amplification of proto-oncogenes such as HER2, EGFR, CCND1, and c-MET, which provide a selective advantage for tumour cell growth and survival through overexpression." (PMID 18349818, 2008). "Ebp1 can also repress the transcription of androgen receptor (AR) and Cyclin D1, through physically binding to the AR or by interacting with the histone deacetylase HDAC2 and the tumor suppressor Retinoblastoma (Rb)." (PMID 19025630, 2008). "In contrast, EGFR, CCND1, and HER2 were amplified in 3.5–6.7% of tumours, often >9 times the normal copy number and frequently amplified in small amplicons indicative of the selective amplification of these genes." (PMID 18349818, 2008). "Previously, cyclin D1-regulated genes from the Lamb profile dataset and Myc-regulated genes from the Coller dataset were each shown to be coordinately expressed with CCND1 and MYC mRNA expression, respectively, in various tumor datasets." (PMID 18350153, 2008). "Oncogenic loci cyclin D1 (CCND1), HER2, and EGFR were amplified in 3.5–6.7% of tumours and frequently contained amplicons <1 Mb." (PMID 18349818, 2008). "The higher expression of IGF1, BCL2, and CCND1 in the BEST prognosis group was unanticipated, as these genes are commonly considered to be tumor- promoting genes." (PMID 17206280, 2007). "Potent tumour suppressors (e.g. PTEN), cell cycle mediators (e.g. CCND1), and cellular respiration genes (e.g. NDUFA1) were found to be tightly regulated in the normal libraries." (PMID 17543121, 2007). "Since cyclin D1 and bcl-xl are thought to be the downstream proteins of activated STAT3, which greatly contributes to tumor progression, we then examined the expression levels of these two proteins by western blot." (PMID 17683579, 2007). "Overexpression of cyclin D1, p21, GST-P, and NF-κB in HBP carcinomas is consistent with similar findings in DMBA-induced experimental tumours and in human OSCC reported in literature." (PMID 18053169, 2007). "Predictions based on tumour grade, or immunohistochemical staining for BCL-2, p27 or cyclin D1, all showed a useful measure of independence from each other." (PMID 15138474, 2004). "Consistent with tumour growth, cyclin D1 protein and PCNA index in tumour tissues were significantly greater in the tumour tissue of G-17 treated mice." (PMID 12189559, 2002).
tumor (continued). "Formalin-fixed and paraffin-embedded tumour tissues resected from 69 NSCLC patients between stages I and IIIa were immunohistochemically examined to detect altered cyclin D1 expression." (PMID 10487623, 1999). "Whereas 20q13 showed a very strong correlation to CCND1 amplification, that of MDM2 was prevalent in MYC-amplified tumours." (PMID 8980401, 1996). "Consequently, MS-444 reduces the expression of HuR targets such as COX-2, cyclin D1, and VEGF, leading to impaired tumor cell proliferation, induction of apoptosis, and suppression of tumor growth in colorectal and pancreatic cancer models." (PMID 41596407, 2026). "In CRC, however, SLC46A1 downregulation induces intracellular folate deficiency, triggering locus-specific DNA hypomethylation at the FOS promoter, which activates oncogenic transcription of key downstream effectors (CCND1, BCL2, PLAU), driving tumor progression." (PMID 41620398, 2026). "Increased cleaved caspase-3 levels and reduced cyclin D1 expression by decreasing the mRNA levels of LIM domain kinase signalling-related targets, such as p-cofilin and phosphorylated LIM domain kinase, that results into inhibition of tumour development." (PMID 40427522, 2025). "Interestingly, compared to normal tissues, SPP1+ TAMs-CAFs regulated tumor cells through the regulation of genes related to HCC tumorigenesis, including CCND1, MYC, CTNNB1, and BAX." (PMID 40230843, 2025). "Given its role in cell cycle regulation (Cyclin D1, Cyclin E) and mitochondrial stress responses, PHB2 may influence the efficacy of TMZ and other chemotherapeutic agents by modulating tumor metabolism and oxidative stress responses." (PMID 40076502, 2025). "The expression analysis showed that ESR1 had no expression difference between normal and tumor groups; BCL2 expression was lower in tumor group (P < 0.001); while AKT1, CCND1, and HIF1A expressions were higher in tumor group compared with those in normal group (all P < 0.001)." (PMID 40552073, 2025). "Additionally, cyclin D1 (CCND1; chr 11q), fibroblast growth factor receptor 3 (FGFR3; chr 4p), and PIK3CA (chr 3q) were amplified in the tumor tissues from patients S390 and S425, S425 and S028, and S425 and S424, respectively." (PMID 41301905, 2025). "In PDX JH-2–002, the combination significantly repressed tumor mitotic activity and proliferation as indicated by mitotic counts and Ki-67 decrease and markedly inhibited p-ERK, DUSP6 and several other downstream effectors (p-RSK, p-S6, p-RB, Cyclin D1)." (PMID 41023593, 2025). "However, a decrease of tumor size and downregulation of the HIF-2α specific genes PAI-1, CCND1, EPO, and GLUT-1 have been reported in ccRCC xenografts treated with PT-2385 (aka MK-3795), a new HIF-2α inhibitor." (PMID 40227577, 2025). "Immunofluorescence staining demonstrated significant reductions in STAT3 and downstream proteins (VEGF, cyclin D1, c-Myc, BCL-2, and PD-L1) post-treatment, confirming D11-PROTAC’s ability to downregulate these proteins in tumor tissues, aligning with its cellular effects." (PMID 40118821, 2025). "We did not observe a nisin Z-dependent effect on the tumor burden or cyclin D1 expression in the colon." (PMID 41051239, 2025). "Ultimately, we identified Acacetin and Asperglaucide as the most effective pharmacologically active ingredients in YYFZBJS for the treatment of NPC, suggesting that they may exert anti-tumor effects through the modulation of PTGS2 and CCND1 expression." (PMID 40302810, 2025). "The tumor cells were positive for CD163, ALK, phosphorylated ERK, and cyclin D1." (PMID 40361876, 2025).
tumor (continued). "For context, Cyclin D1 is an allosteric master regulator of the cell cycle, more specifically it works in concert with the activating cyclin-dependent kinases (CDK4/6) to allow for G1/S checkpoint progression 50,51 and hence tumour growth." (PMID 40765817, 2025). "To investigate whether the nanomaterials inhibited tumor cell glycolysis as expected, we first performed Western blotting to verify the expression of PKM2 downstream target proteins, c-Myc and Cyclin D1." (PMID 41272362, 2025). "Furthermore, cyclin D1 led to retinoplastoma protein (pRB) phosphorylation and drove RCC from the G1 phase to the S phase, thereby accelerating tumor cell proliferation." (PMID 40725144, 2025). "Taking LIHC and UVM as examples, FAM72B may promote tumor cell proliferation in LIHC by activating cell cycle-related genes (e.g., Cyclin D1) and accelerating the cell cycle process." (PMID 41153357, 2025). "Cyclin D1 is negative or expressed in <10% of tumor nuclei, an important discriminator from high-grade ESS, which shows strong, diffuse nuclear positivity (>70%)." (PMID 41464215, 2025). "Like others, we have shown that CCND1 amplification status does not add further information about DFS or OS to the established biomarkers of tumor size — lymph-node involvement, and grading." (PMID 39586971, 2025). "Furthermore, α-syn lowers MGMT and cyclin D1 (CCDN1) expressions and reduces tumor development in allografted mice." (PMID 40108111, 2025). "Western blot analysis of tumor tissues confirmed that fedratinib downregulated key signaling molecules and effector proteins, including JAK2, p-JAK2, STAT3, p-STAT3, vimentin, survivin, and cyclin D1." (PMID 41476794, 2025). "In this model, garcinol decreased tumor size and tumor incidence in the colon, and decreased COX-2, cyclin D1, and VEGF via inhibition of the extracellular signal-regulated protein kinase 1/2, phosphatidylinositol 3 kinase/Akt/p70 ribosomal S6 kinase, and Wnt/β-catenin signaling pathways." (PMID 41303402, 2025). "The subsequent WB results indicated that SH decreased the levels of the proliferation-promoting proteins cyclin D1 and MCM2 and increased the expression of the proliferation-inhibiting factor p21, further confirming the influence of SH on tumor cell proliferation." (PMID 41444284, 2025). "Meanwhile, the expression of CCND1 and E2F target genes was downregulated in ASO-circFOXK2-treated tumors, strengthening the functional importance of these genes in circFOXK2-mediated tumor growth." (PMID 40233410, 2025). "The STAT3 signaling pathway, crucial for tumor growth and survival, was significantly inhibited by faberidilactone A, as evidenced by reduced STAT3 phosphorylation and downregulation of downstream targets such as cyclin D1 and Mcl-1." (PMID 40076318, 2025). "PLK4 expression in the tumor tissues markedly varied with the degree of differentiation, and it was notably elevated in poor-differentiated regions compared with well-differentiated regions, wherein the expression of PHOX2B, CXCR4, and cyclin D1 was higher." (PMID 40860200, 2025). "However, overexpression of cyclin D1 leads to cell cycle checkpoint failure and CDK dysregulation, which promotes tumor initiation and progression." (PMID 40948788, 2025). "It is worth noting that, in the present study, CCND1 was not differentially expressed in canine tumours and was significantly underexpressed in human OSA (p = 0.008187)." (PMID 40566602, 2025).
tumor (continued). "The group of Kowshik demonstrated that astaxanthin could hinder tumor progression by attenuating JAK/STAT signaling and its target molecules, including VEGF, cyclin D1, and MMP in the HPV-induced tumor models." (PMID 38952548, 2024). "In addition, groups SeNPs loaded P. crinita extract (25, 50 mg/kg) revealed a more significant decrease in the Cyclin D1 levels (54.7% and 80.8%), in comparison with untreated SEC-mice (tumor control group)." (PMID 38469406, 2024). "The three tumor clusters highly expressed CDK4, CCND1, and MYCN, respectively." (PMID 38181797, 2024). "Collectively, our findings indicate that STOML2 facilitates the recruitment of TRADD and sustains NF-κB activity to upregulate CCND1, VEGFC and PD-L1, which consequently leads to tumor proliferation, angiogenesis, immune escape and poorer clinical outcomes in human in CRC." (PMID 38214751, 2024). "Furthermore, overexpression of Cyclin D1 (CCND1) leads to dysregulation of cyclin-dependent kinase (CDK) activity, rapid cell growth under conditions of restricted mitotic signaling and ultimately tumor growth." (PMID 38817869, 2024). "Tumor sequencing revealed LOH in CHEK2 and ATM, as well as CCND1 and GAB2 amplifications." (PMID 38091153, 2024). "The present study demonstrated that ART1 knockdown significantly inhibited IL-6-induced p-STAT3 and its target proteins, c-Myc, cyclin D1 and Bcl-xL (amp and E, 3 A-D, 7D & E), the proliferation of CRC cells and the growth of transplanted tumours in a mouse model." (PMID 38504172, 2024). "By accelerating CCND1 degradation through SKP2-mediated ubiquitination, MAT1A depletion disrupts the delicate balance between cell proliferation and apoptosis, thereby impairing tumor growth." (PMID 39438468, 2024). "The expression of c-Myc, Cyclin D1, and Cox-2 was not significantly different in these two tumor tissues." (PMID 38992029, 2024). "Moreover, the levels of proteins involved in cell proliferation (p-Stat3, PCNA, Ki67, and cyclin D1) and cell migration (MMP2) were analyzed in the tumor tissues." (PMID 38441416, 2024). "Upregulated NAP1L1 increases the expression of the cell cycle protein cyclin D1 (CCND1) by recruiting heparin-binding growth factor (HDGF) and interacting with c-Jun, thereby enhancing the proliferation of HCC cells and promoting tumour progression." (PMID 38538582, 2024). "This particular tumor line has a robust HRR response to DNA damage and may be recruiting Cyclin D1, which is consistent with these results." (PMID 38386805, 2024). "MMP11 was highly expressed in the cancerous ductal epithelium and might act as a tumor promoter in PDAC, stimulating cyclin-dependent kinase 4 and cyclin D1." (PMID 38572434, 2024). "QUE stimulated the level of cyclin D1 in normal cells, not in tumor cells, which increased the levels of cellular p21 and Cdk2." (PMID 39459023, 2024). "Levels of β-catenin, c-MYC, and CCND1 were negatively correlated with miR-150 overexpression suggesting that miR-150 might decrease CRC growth and operate as a tumor suppressor by blocking β-catenin pathway." (PMID 38632250, 2024). "Indeed, MCLs express the neoplasm markers of mature B cells, namely CD19, CD20, CD22, CD79-A, and Cyclin D1." (PMID 38828423, 2024). "Moreover, solanine significantly downregulates key inflammatory and proliferative markers, such as iNOS, IL-6, Cyclin D1, and PCNA, reducing tumor growth and inflammation." (PMID 39124760, 2024). "Furthermore, the correlation between the expression of the selected miR-1246 and miR-150-5p (with the lowest FDR value) in serum, and that of CCND1 and E2F1 was analysed in tumour tissue." (PMID 37935712, 2023). "Similarly, protein levels of PCNA, cyclin D1, cyclin E, and MMP-9 decreased, whereas TNFα expression increased in the tumor area of the HCT-116 xenograft in nude mice." (PMID 36979011, 2023). "To identify novel tumor biosignatures expressed in HNSC, we established CCND1-related ceRNAs." (PMID 37481637, 2023).